STAT3 (signal transducer and activator of transcription 3)
Diseases named in the same sentence as STAT3 in open-access papers (continued):
Sharing a sentence is not in itself a finding about the gene and the disease.
tendinopathy (5 papers, 2019 to 2024). "In the inflammatory response of tendinopathy, STAT3 has a dual regulatory role, but the specific mechanism of action is still unclear." (PMID 37744452, 2023). "In particular, NF-κB, NLRP3, p38/MAPK, and signal transducer and activator of transcription 3, four common signaling pathways in tendinopathy inflammatory response, play a crucial role in the regulation and transcription of inflammatory factors." (PMID 37744452, 2023). "Furthermore, the involvement of MMPs, ICAM-1, signal transducer, and STAT3 has been reported in the pathogenesis of tendinopathy." (PMID 39012676, 2024). "STAT1 and STAT3, members of the cytoplasmic family of transcription-factor (STAT) signal-transducers and activators, have been associated with inflammatory pathologies, including tendinopathy." (PMID 36499497, 2022). "In terms of drugs, plenty of drugs like aspirin were found to be conducive to tendinopathy treatment through many signaling pathways, such as JNK/STAT3 pathway." (PMID 37064249, 2023). "In summary, the present study demonstrated that aspirin inhibited the inflammation and scar formation in tendinopathy tendon, and the process was related to JNK/STAT‐3 signalling pathway." (PMID 31225686, 2019).
vasculitis (5 papers, 2020 to 2021). "To determine the possible upstream regulators of STAT3 in the LCWE-induced mouse model of KD vasculitis, we utilized our previously published RNA-seq data (GSE141072) from the abdominal aorta of mice treated with PBS, LCWE or LCWE and anakinra." (PMID 33897686, 2021). "To test the role of STAT3 in LCWE-induced KD vasculitis, we examined the impact of treatment with the small molecule STAT3 inhibitor, Stattic, on disease pathogenesis." (PMID 33897686, 2021). "For example, abatacept in CTLA4 haploinsufficiency, LRBA and DEF6 deficiencies; tocilizumab in STAT3 GOF; JAK inhibitors in STAT3 and STAT1 GOF patients; alemtuzumab for CD25 deficiency; PIK3δ inhibitors for APDS or anti-TNFα therapy for vasculitis in ADA2 deficiency." (PMID 34447369, 2021). "Like STAT3, we found that IL-6 was enhanced in the LCWE model of KD vasculitis and its expression was reduced with anakinra treatment." (PMID 33897686, 2021). "Using the LCWE-induced mouse model of KD vasculitis, we show that despite high IL-6 and STAT3 expression, suppression of these factors does not reduce the development of the cardiovascular lesions." (PMID 33897686, 2021). "Cysts were mainly found in the LCH patients (n = 6) (Fig. 3B1, B2), and also in the patients with CTD, vasculitis, DAH with no proof of systemic disease, COPA syndrome, CVID, CGD, STAT3 mutation, and surfactant dysfunction disorders." (PMID 31969166, 2020). "However, blockade of STAT3 or IL-6 did not alter acute disease in the LCWE-induced mouse model of KD vasculitis." (PMID 33897686, 2021).
adrenocortical carcinoma (4 papers, 2019 to 2024). "High-throughput screen identified niclosamide as potent Stat3 inhibitor, that suppresses Stat3 phosphorylation at Tyr705 in adrenocortical carcinoma and prostate cancer." (PMID 31383893, 2019).
alcohol (4 papers, 2019 to 2022). "In addition, IL-22 activates the hepatic signal transducer and activator of transcription 3 (STAT3), decreases the hepatic expression of fatty acid transport protein, and ameliorates alcohol related liver inflammatory injury and hepatic oxidative stress." (PMID 35308525, 2022). "In addition, Stat3 in hepatocytes is involved in induction of CXCL2 and CCL2 expression followed by increased infiltration of inflammatory cells in an alcohol liver injury model." (PMID 31718093, 2019). "Furthermore, our study indicated that M2 macrophages, CD4+ T cells, NK cells, B cells and monocytes may participated in the development of alcohol-related HCC, which may involve the activation of STAT3 and NF-kB transcription factors or the accumulation of ROS and iron." (PMID 34646769, 2021).
alcoholic fatty liver disease (4 papers, 2020 to 2025). Lipid infiltration of the hepatic parenchymal cells that is due to alcohol abuse. "Moreover, we found that kefir peptides improved non-alcoholic fatty liver diseases through manipulation of the JAK2/STAT3 and JAK2/AMPK signaling pathways in a high fructose-induced fatty liver animal model." (PMID 32472055, 2020). "The findings collectively indicate that inhibition of the JAK2/STAT3 pathway mitigates stress-induced hepatic inflammatory injury by reprogramming macrophage polarization dynamics, aligning mechanistically with Jinmei Yao’s observations in non-alcoholic steatohepatitis models." (PMID 41369337, 2025).
aortic aneurysm (4 papers, 2021 to 2025). A ruptured aneurysm located in the wall of the proximal portion of the descending aorta proceeding from the arch of the aorta. "The JAK2/STAT3 pathway is involved in various biological processes, including inflammation and tissue damage and repair, and is critical in the formation and development of AD and aortic aneurysm." (PMID 40278823, 2025).
astroglioma (4 papers, 2018 to 2024). "The cytokine oncostatin M promoted the expression of AM in astroglioma cells favoring the phosphorylation of activator of transcription-3 (STAT-3), nuclear translocation, and DNA binding to AM promoter." (PMID 36980580, 2023). "The expression of AM is controlled by STAT-3 in these cells, and AM also increases the migration of astroglioma cells." (PMID 36980580, 2023). "Moreover, in phaeochromocytoma, the involvement of AM2 in tumor growth must be elucidated, and the role of STAT-3 in invasion and metastasis must be investigated in tumors other than astroglioma." (PMID 36980580, 2023). "The cytokine oncostatin, after inducing STAT-3 (signal transducer and activator of transcription-3) phosphorylation, promotes the expression of AMD in astroglioma cells, and this peptide also increases their migration." (PMID 39063232, 2024). "In astroglioma cells, OSM induces an approximately three-fold increase in VEGF, while OSM and IL-1β together induce an approximately seven-fold increase of VEGF after 48 hours in astroglioma cells, in a STAT3 dependent manner." (PMID 37841259, 2023).
Atrophy (4 papers, 2014 to 2024). Any weakening or degeneration, especially through lack of use. "Exo-miR-214 can significantly inhibit the expression level of PTEN, increase the protein expression levels of p-JAK2 and p-STAT3 and the ratio of p-JAK2/JAK2 and p-STAT3/STAT3, also MDSCs-derived exosomes with overexpressed miR-214 can reduce the occurrence of denervated muscle atrophy." (PMID 37305554, 2023). "Interestingly, it is found that HuR interacts directly with STAT3 mRNA-3′UTR, which is close to the miR-330 seed element, resulting in obstructing the translation regulated by miR-330, implying that their rival relation could offer novel therapy alternatives for STAT3-induced muscle atrophy." (PMID 39404384, 2024).
chronic atrophic gastritis (4 papers, 2015 to 2025). Atrophic gastritis that is persistent and long-standing. "Previously, in a study assessing the effects of maximal gp130/STAT3 activation on the gastric mucosa, we reported that systemically administered IL-11 (20μg/day) caused gastric atrophy and mucus metaplasia through STAT3 activation, and coincident with elevated IL-1β expression." (PMID 25528766, 2015). "However, consistent with previous reports, IL-1RT1 signaling is required for IL-6 expression during STAT3 induced gastric atrophy." (PMID 25528766, 2015).
clear cell carcinoma (4 papers, 2018 to 2023). "In the context of OvCa, cucurbitacin-E was found to suppress clear cell carcinoma ES-2 cell proliferation and induce apoptosis, which was accompanied by decreased expression of STAT3." (PMID 37173951, 2023). "When cells are subjected to hypoxic conditions, STAT3 phosphorylation is significantly induced; however, STAT3 knockdown reduced proliferation of A2780 endometrioid/clear cell carcinoma cells." (PMID 37173951, 2023). "Moreover, TRIM47 knockdown suppressed STAT3 phosphorylation, which resulted in decreased expression of Myc mRNA and abrogated cell growth and survival in both clear cell carcinoma SKOV3 and HGSOC OVCAR3 cell lines." (PMID 37173951, 2023). "In this study, we explored the activation of JAK2/STAT3 pathway in serous HEY and clear cell carcinoma TOV21G cell lines in vitro by Western Blot and immunofluorescence in response to the concentration of paclitaxel which inhibited cell growth by 50% (GI50) (HEY: 0.05ng/mL, TOV21G: 0.01ng/mL)." (PMID 29682172, 2018).
clear cell ovarian carcinoma (4 papers, 2019 to 2022). "A Japanese study found that p-STAT3 expression was correlated with OS, and the activation of the JAK2/STAT3 pathway is critical for the survival of clear-cell ovarian cancers." (PMID 33029256, 2020). "Inhibition of STAT3 signaling leads to apoptosis of ovarian clear cell carcinoma and decreased BCL-2 expression." (PMID 31861720, 2019). "The activation of STAT3 pathway was, in particular, related to overall survival in ovarian clear cell carcinoma patients." (PMID 31861720, 2019). "siRNA mediated inhibition of IL-6R or anti-human IL-6R antibody (tocilizumab) reduced pY-STAT3 and MMP-9 expression levels suggesting that interference of STAT3 signaling in ovarian clear cell carcinoma could be an effective therapeutic strategy." (PMID 31861720, 2019). "A histotype-specific approach to target ovarian clear cell carcinoma with the STAT3 pathway might be an avenue worth pursuing." (PMID 31861720, 2019). "The upregulation of IL-6, STAT3, HIF-1α observed in ovarian clear cell cancer samples indicates an IL-6/STAT3/HIF1α/VEGF autocrine activation loop in EOC thereby facilitating tumor angiogenesis." (PMID 35401182, 2022).
Coagulopathy (4 papers, 2021 to 2024). "Suppression of STAT1 pathway leads to compensatory STAT3 hyper-activation, which is associated with elevating plasminogen activator inhibitor-1 (PAI-1), and consequently leads to affliction with coagulopathies." (PMID 36656874, 2023). "This review also emphasized the “STAT3 and Coagulopathy” with the production Tissue Factor induced by CRP which may have activated by STAT3 and prime the initial phase of coagulation." (PMID 35794133, 2022). "However, more importantly, it linked the observed changes with processes that could potentially impact the clinical outcomes of HF such as coagulation disorder and JAK/STAT3 pathway." (PMID 39457580, 2024).
cystic fibrosis (4 papers, 2018 to 2025). Autosomal recessive disorder caused by pathogenic variants in the CFTR gene (cystic fibrosis transmembrane conductance regulator), which encodes a chloride and bicarbonate channel expressed in epithelial cells, and follow the diagnosis criteria. "Anti-inflammatory responses to iPR treatment have been documented in Chinese hamster ovary (CHO) cells where they are mediated through binding to adenosine A3 receptor and in cystic fibrosis cell lines via inhibition of NFκB and STAT3 pathways." (PMID 38932119, 2024). "While their study focused on the lungs and cystic fibrosis, our findings demonstrated the reduction of phosphorylated STAT3 in the kidneys of a salt-induced hypertensive model, adding to the growing evidence of hAAT’s potential as a therapeutic agent across multiple organ systems." (PMID 40723823, 2025). "Consequently, a disturbance in the control of the complex EGFR/ADAM17/STAT3 pathway would likely play a role in Cystic Fibrosis and COPD chronic lung disease." (PMID 29540993, 2018).
developmental delay (4 papers, 2024 to 2025). "ASCC3 is involved in the regulation of signal transducer and activator of transcription 3 (STAT3) and interferon response genes, and variants are associated with developmental delays and increased pTau." (PMID 40386807, 2025). "Neurological manifestations, mainly cognitive delay, are frequent and assist in distinguishing this syndrome from other HIES, namely DOCK8 immunodeficiency syndrome or autosomal dominant HIES due to STAT3 deficiency." (PMID 40698220, 2025).
dry eye (4 papers, 2016 to 2025). "Therefore, in dry eye patients, IL6 could be a biologic marker, and regulating IL6 though the IL6/JAK/STAT3 signaling pathway could be an effective therapeutic target." (PMID 27555966, 2016).
E. coli infection (4 papers, 2016 to 2023). "In a murine model of infection with Citrobacter rodentium, a pathogen that mimics Escherichia coli infection in humans, the expression of AMPs, such as RegIIIγ and Pla2g2a is dependent on STAT3 activation in the intestine." (PMID 27633343, 2016). "Results showed that SEP promoted bacterial clearance by enhancing phagocytosis by macrophages during E. coli infection in vitro, but was inhibited by TLR4 specific inhibitor TAK-242, STAT3 inhibitor Stattic or blockade of CD64." (PMID 35370674, 2022). "A recent study published in Nature highlighted the crucial STAT3‐dependent role of IL22 in crypt regeneration and PC maturation, and pointed to the activation in PCs of IL22–STAT3 signaling response after adherent‐invasive E. coli infection." (PMID 36573340, 2023).
enteritis (4 papers, 2018 to 2023). Inflammation of the small intestine. "IL-10 gene-deficient mice (IL10 -/- mice) and macrophage-specific Stat3-deficient mice (LysM-cre; Stat3 f/- mice) spontaneously develop enteritis." (PMID 36845090, 2023). "In this study, the expression of Smad3 and NFAT2 in the Treg-infusion group was significantly higher than that in the enteritis group, but the expression of Stat3 was lower than that in the enteritis group." (PMID 30364052, 2018). "Besides, the significant anti-viral activity of IL-22 could be a novel therapeutic against multiple enteric diarrhea viruses in IPEC-J2, such as PEDV, PoRV and TGEV, which were mediated by the activation of the STAT3 signal pathway." (PMID 37924089, 2023).
focal segmental glomerulosclerosis (4 papers, 2021 to 2025). A renal disorder characterized by sclerotic lesions in the glomeruli. "In addition, STAT3 activation has been shown to promote the progression of focal segmental glomerulosclerosis, which is manifest in patients with SPLIS." (PMID 33755599, 2021). "In focal segmental glomerulosclerosis (FSGS), the JAK–STAT signaling pathway is activated, with increased phosphorylation of STAT1 and STAT3 in both the glomerulus and renal tubulointerstitium." (PMID 40384344, 2025). "Infiltrating immune cells perpetuated injury by stimulating collagen deposition and α-SMA expression viainterleukin-6 (IL-6)/signal transducer and activator of transcription 3 (STAT3)-mediated pathways, as shown in podocyte injury in focal segmental glomerulosclerosis." (PMID 40276370, 2025).
Gastric Metaplasia (4 papers, 2013 to 2022). Intestinal metaplasia of the gastric mucosa is an intermediate precancerous gastric lesion in the gastric cancer cascade from chronic gastritis and atrophy to dysplasia and adenocarcinoma. "IL33 is mainly induced by chronic phosphorylation of signal transducer and activator of transcription 3 (STAT3), and previous studies have shown that overactivated STAT3 is involved in gastric inflammation and can lead to Th2-mediated gastric metaplasia." (PMID 36275647, 2022). "However, STAT3 was highly activated, leading to Th2-mediated gastric metaplasia, suggesting that IL33 may be capable of driving gastric disease under specific circumstances." (PMID 28210674, 2015). "Given that IL-1β induces gastric metaplasia and stimulates expression of the proto-oncogene IL-6 in various cell types, we hypothesized that IL-1β induces expansion of the SPEM phenotype by stimulating proliferation and IL-6 expression along with phosphorylation of STAT-3 (pSTAT-3)." (PMID 23520544, 2013).
herpesvirus infections (4 papers, 2018 to 2025). "Meanwhile, some herpesvirus infections are associated with STAT3." (PMID 32201498, 2018).
histoplasmosis (4 papers, 2011 to 2025). A disease caused by the fungus Histoplasma capsulatum. "We report a young child ultimately presenting with disseminated histoplasmosis and a novel STAT3 variant in the SH2 domain." (PMID 22126402, 2011). "This case of STAT3-HIES also highlights the inherent susceptibility of these patients to intracellular organisms endemic to the region (in our case, histoplasmosis)." (PMID 22126402, 2011).
Hyperkeratosis (4 papers, 2021 to 2025). Hyperkeratosis is a histopathological term defining a thickened stratum corneum and may be present in many different skin conditions, with many possible overlaps. "In this direction, when the skin of Cdsn−/− was grafted in nude mice, to study disease progression to adulthood, it was shown that Cdsn−/− had signs of acanthosis, hyperkeratosis, parakeratosis and Stat3 nuclear localization, resembling a psoriatic phenotype." (PMID 40943523, 2025). "We observed a significant increase in inflammatory factors (such as TNF-α, IL-1β, CXCL1, CXCL2, CCL4, and TLR7) and exacerbates hyperkeratosis and keratosis in STAT3 mice." (PMID 37465147, 2023). "Supplementation of the STAT3 overexpressing model with activated or naïve T cells, did not significantly increase S100A7 levels, however, activated T cells in contrast to naïve T cells induced strong parakeratosis and hyperkeratosis, both hallmarks of psoriatic skin." (PMID 40678130, 2025).
hypopharyngeal cancer (4 papers, 2016 to 2022). Carcinoma, predominantly squamous cell, arising from the epithelial cells of the hypopharynx. "Given the central role of STAT3 pathway in HNSCC, despite its complexity, our data provide supportive evidence of STAT3 inhibition as a preventive and therapeutic approach in hypopharyngeal cancer." (PMID 34850540, 2022). "We also show that all three STAT3 inhibitors, with STA‐21 having the most profound effect, can effectively suppress the continuous production of cancer‐related molecules, IL6, TNF, RELA(p65), EGFR, BCL2 and STAT3, previously associated with hypopharyngeal cancer, caused by acidic bile." (PMID 34850540, 2022). "We also showed that activation of p38 leads to downregulation of JNK and its downstream target STAT3, leading to decreased expression of Bcl-2, which in turn, results in inhibition of cell growth and induction of apoptosis and autophagy in metformin treated-hypopharyngeal cancer FaDu cells." (PMID 33652909, 2021).
infectious colitis (4 papers, 2015 to 2021). A viral or bacterial infectious process affecting the large intestine. "The defective STAT3 signaling pathway leads to susceptibility to infectious colitis and bacterial peritonitis and leptin treatment restored the protective mucosal immune response in C. difficile colitis by the STAT3 inflammatory pathway." (PMID 30534129, 2018). "To examine the role of Stat3 for antimicrobial defense mechanisms during gastrointestinal infections in vivo, we used the C. rodentium induced infectious colitis mouse model." (PMID 25799189, 2015). "Moreover, a recent study has demonstrated that activation of signal transducer and activator of transcription factor 3 (STAT3) was required for IL-22 production by Th22 cells and was responsible for effective host clearance of infectious colitis." (PMID 26793707, 2015).
juvenile idiopathic arthritis (4 papers, 2023 to 2025). Juvenile idiopathic arthritis (JIA) is the term used to describe a group of inflammatory articular disorders of unknown cause that begin before the age of 16 and last over 6 weeks. "For example, hsa-miR-21 suppresses the expression of STAT3 and is down-regulated in juvenile idiopathic arthritis." (PMID 36830652, 2023). "Our findings are supported by Li and Zeng, who described the effective regulatory effects of miR-21 on the JAK-STAT signaling pathway via the suppression of STAT3 in juvenile idiopathic arthritis patients." (PMID 36980823, 2023).